TRBV10-3 (T cell receptor beta variable 10-3)
Description:
V region of the variable domain of T cell receptor (TR) beta chain that participates in the antigen recognition. Alpha-beta T cell receptors are antigen specific receptors which are essential to the immune response and are present on the cell surface of T lymphocytes. Recognize peptide-major histocompatibility (MH) (pMH) complexes that are displayed by antigen presenting cells (APC), a prerequisite for efficient T cell adaptive immunity against pathogens. Binding of alpha-beta TR to pMH complex initiates TR-CD3 clustering on the cell surface and intracellular activation of LCK that phosphorylates the ITAM motifs of CD3G, CD3D, CD3E and CD247 enabling the recruitment of ZAP70. In turn ZAP70 phosphorylates LAT, which recruits numerous signaling molecules to form the LAT signalosome. The LAT signalosome propagates signal branching to three major signaling pathways, the calcium, the mitogen-activated protein kinase (MAPK) kinase and the nuclear factor NF-kappa-B (NF-kB) pathways, leading to the mobilization of transcription factors that are critical for gene expression and essential for T cell growth and differentiation. The T cell repertoire is generated in the thymus, by V-(D)-J rearrangement. This repertoire is then shaped by intrathymic selection events to generate a peripheral T cell pool of self-MH restricted, non-autoaggressive T cells. Post-thymic interaction of alpha-beta TR with the pMH complexes shapes TR structural and functional avidity.
Synonyms: TRBV103; TCRBV10S3; TCRBV12S1A1N2
Gene: T-cell receptor variable (V) gene on chromosome 7 (142,544,212 to 142,544,685, forward strand). Ensembl gene ENSG00000275791.
Subcellular location: Cell membrane
Gene Ontology:
Biological process: cell surface receptor signaling pathway
Cellular component: plasma membrane
Homologues: Orthologues: macaque TRBV10-3 (77% identical), mouse Trbv13-3 (62% identical), mouse Trbv13-1 (61% identical), mouse Trbv13-2 (61% identical). Paralogues in human: TRBV10-1 (83% identical), TRBV10-2 (79% identical), TRBV6-7 (61% identical), TRBV6-2 (61% identical), TRBV6-5 (61% identical), TRBV6-4 (60% identical), TRBV24-1 (58% identical), TRBV6-6 (58% identical), TRBV6-1 (57% identical), TRBV25-1 (55% identical), TRBV6-8 (55% identical), TRBV27 (54% identical), and 39 more.